CRP (C-reactive protein)
Diseases named in the same sentence as CRP in open-access papers (continued):
Sharing a sentence is not in itself a finding about the gene and the disease.
tuberculosis (continued). "Two inflammatory biomarkers, C-reactive protein (CRP) and procalcitonin, have shown some diagnostic utility for bacterial respiratory infections, and CRP has high sensitivity but low specificity for diagnosing HIV-associated tuberculosis." (PMID 30107791, 2018). "CRP and procalcitonin were both found to have limited value in distinguishing between the three common infections due to widely overlapping distributions, particularly between tuberculosis and CAP." (PMID 30107791, 2018). "C-reactive protein (CRP) and procalcitonin have shown diagnostic utility for respiratory tract infections, however few studies have focussed on their ability to distinguish between tuberculosis, CAP, and PJP in HIV-infected inpatients." (PMID 30107791, 2018). "For laboratory examinations, when compared to control subjects, patients with active tuberculosis showed an obvious increase in the levels of C-reactive protein (CRP), erythrocyte sedimentation rate (ESR), and absolute leucocyte, platelet and monocyte counts (p all <0.001)." (PMID 28424495, 2017). "Previous studies in chronic disease have demonstrated the ability of CRP to predict cardiovascular events in patients with arteriosclerotic diseases, treatment failure in tuberculosis or human immunodeficiency virus infection, and disease progression in ILD with systemic scleroderma." (PMID 26635226, 2015). "The relationshipbetween CRP and albumin levels might be a useful tool for assessing the bacteriologicalconversion in patients with tuberculosis." (PMID 25029650, 2014). "Furthermore, the erythrocyte sedimentation rate (ESR), adenosine deaminase (ADA) and C-reactive protein (CRP) levels, tuberculosis anti-body (TBAB) and γ-interferon antibody release test for Mycobacterium tuberculosis in the ascites were all normal." (PMID 24348779, 2014). "However, the high negative predictive value of any elevated CRP (0.96 for participants with confirmed tuberculosis and 0.72 for all with tuberculosis) suggests that a normal CRP would be useful for ruling out tuberculosis." (PMID 21249220, 2011). "CRP may have a role in algorithms for the evaluation of SNTB in sub-Saharan Africa where the need for novel tuberculosis diagnostics is greatest." (PMID 21249220, 2011). "C-reactive protein (CRP) was evaluated as a biomarker for pulmonary tuberculosis (TB) diagnosis and treatment response monitoring in 292 Kenyan children." (PMID 41660661, 2026). "We assessed the utility of C-reactive protein (CRP) as a screening test for tuberculosis (TB) in PLHIV." (PMID 35806852, 2022). "Our study helps to reiterate the value of CRP as a screening tool for TB in PLHIV and shows its validity in patients who are on anti-retroviral therapy as well as its utility in extra-pulmonary tuberculosis." (PMID 35806852, 2022). "One month after treatment completion (i.e., 7 months after M. tuberculosis infection), coinfection with SIV led to TB reactivation in the majority of untreated animals, as demonstrated by increased CRP levels." (PMID 35862216, 2022). "However, treatment of PCM lasts longer than that of tuberculosis, which could explain the persistence of high CRP levels even after six months of treatment." (PMID 31877169, 2019). "Studies on patients with tuberculosis have demonstrated that CRP aid in the diagnosis of TB and also act as a marker of smear-positive persistence at one month after treatment." (PMID 31877169, 2019). "The ESR and CRP are of a high level, which represent that the tuberculosis bacillus are active and TB toxicity symptoms are serious." (PMID 28407019, 2017). "The C - reactive protein (CRP) response is often measured in patients with active tuberculosis (TB) yet little is known about its relationship to clinical features in TB, or whether responses differ between ethnic groups or with different Mycobacterium tuberculosis (M.tb) strain types." (PMID 27287260, 2016).
tuberculosis (continued). "Erythrocyte sedimentation rate (ESR) and C-reactive protein (CRP) were used to evaluate the activity of tuberculosis (TB)." (PMID 26242404, 2015). "However, it was very difficult to distinguish cryptococcal lymphadenitis from lymphoma and tuberculosis in our case, despite the laboratory test results (elevated erythrocyte sedimentation rate, plasma and urinary β2-MG levels, and C-reactive protein and fibrinogen)." (PMID 23862091, 2013). "Pre-treatment serum CRP concentrations have a high sensitivity for the diagnosis of active tuberculosis among smear-negative tuberculosis suspects and was recently shown to be a risk factor for sputum smear conversion among participants in a micronutrient trial in Nigeria." (PMID 22238625, 2012). "Screening CRP may be most effectively used in early in diagnostic algorithms in primary care settings to triage smear-negative tuberculosis suspects for onward referral for chest radiograph and clinician review." (PMID 21249220, 2011). "The diagnostic utility of CRP in smear-negative tuberculosis suspects in a high HIV prevalence setting is unknown." (PMID 21249220, 2011). "Ultimately, the model incorporated systemic symptoms of tuberculosis, altered consciousness, neurological deficits, meningeal irritation, CSF protein levels, T-SPOT results, and CRP." (PMID 41313026, 2026). "We report a rare case of non-articular osseous sarcoidosis with progressive pulmonary lesions and persistently normal inflammatory biomarkers (ACE, CRP, ESR, IL-2, and TNF-α) that required differentiation from metastatic bone tumors and tuberculosis." (PMID 40361953, 2025). "The data of CRP in Tianhou showed that CRP was significantly increased, indicating that after puncture and drainage of TB cold abscess, the symptoms of TB poisoning were rapidly relieved, and the body’s own immune system was fully activated, which promoted the ability to clear M tuberculosis." (PMID 40184121, 2025). "There have also been promisingefforts to develop ECL biosensors for point-of-care applications,such as lateral flow devices for CRP and IFN-γ detection, asdiscussed in the Electrochemiluminescence-Based Biosensorsfor Tuberculosis Biomarkers section." (PMID 40202785, 2025). "Compared with the COPD group, the BE-FAO group had higher neutrophil counts in the blood and BAL samples, higher C-reactive protein (CRP) levels, more exacerbation episodes in the past year, and a higher frequency of prior tuberculosis." (PMID 39143556, 2024). "As all patients received regular anti-tuberculosis treatment before and after surgery, ESR and CRP indicators maintained at normal levels 1 week after surgery." (PMID 39741498, 2024). "The highest‐serum CRP levels were also observed in septic patients followed by common bacterial infection with tuberculosis, and the correlation among PCT, CRP, WBC, NEU%, and ESR was low (Pearson correlation R < 0.226)." (PMID 39305165, 2024). "With the extension of anti-tuberculosis treatment time, the inflammation is gradually controlled (ESR and CRP are decreased)." (PMID 37316645, 2023). "Criteria (ADA of 50 and L/N ratio of 0.75) were evaluated by quantile subgroups according to age, C-reactive protein (CRP), white blood cell (WBC), and lactate dehydrogenase (LD) by the Monte Carlo simulation method to diagnose tuberculosis." (PMID 37864205, 2023). "Compared with individuals without confirmed tuberculosis, those with tuberculosis (331, 66.9%) were significantly younger and were more likely to report a history of weight loss and have apical radiological abnormalities, lower baseline hemoglobin, and higher C-reactive protein." (PMID 36668920, 2022). "After anti-tuberculosis drug treatment for 18 months, the patient was considered to be cured, according to normal physical and imaging examinations and ESR and CRP levels." (PMID 32766226, 2020).
tuberculosis (continued). "The patient was then treated with enhanced tetrad anti-tuberculosis strategy (including isoniazid, rifampicin, pyrazinamide, and streptomycin) for 2 weeks, after which the ESR reduced to 42 mm/h and CRP reduced to 17 mg/L." (PMID 33208114, 2020). "Elevated CRP is known to occur in all three of our target infections in individuals with HIV, and our finding that CRP concentrations were highest in CAP, follwed by tuberculosis, and lowest in PJP, is consistent with previous studies." (PMID 30107791, 2018). "Highest receiver operating characteristic areas under the curve for CRP and procalcitonin were for PJP versus tuberculosis and PJP versus CAP (0.68 and 0.71, and 0.74 and 0.69 respectively)." (PMID 30107791, 2018). "Aside from the patient with recurrent tuberculosis, the remaining 44 patients’ ESR and CRP returned to normal within three months’ follow-up." (PMID 29420648, 2018). "A CRP cut-off of 147 mg/L had high specificity for discriminating PJP from CAP, and high sensitivity for discriminating PJP from tuberculosis." (PMID 30107791, 2018). "Increasing CRP and ESR serum levels were reported as potential tuberculosis markers in patients with (−) sputum AFB." (PMID 26823075, 2016). "Bone graft fusion and instrumentation failure were monitored by radiography, and tuberculosis activity was monitored by erythrocyte sedimentation rate (ESR) and C-reactive protein testing." (PMID 26862044, 2016). "Thus the aim of this study was to determine the levels of CRP, Neopterin and B2M in relation to pulmonary tuberculosis disease severity at recruitment and changes in response to TB treatment in a cohort of TB patients from The Gambia." (PMID 26951717, 2016). "On one hand, diseases like tuberculosis, tumor, systematic or local infections can also result in the elevation of ESR and CRP." (PMID 25799575, 2015). "Fractalkine, IL-17, IL-6, IL-9, MIP-1β, CRP, VEGF, and IL-5 levels in saliva and IL-6, IL-2, SAP, and SAA levels in serum were significantly higher in tuberculosis patients (P < 0.05)." (PMID 24327799, 2013). "The median CRP quotient was 15.4 (IQR 7.2; 23.3) in the confirmed tuberculosis group, 5.8 (IQR 1.4; 16.0) in the group with possible tuberculosis, and 0.7 (IQR 0.2; 2.2) in the group without tuberculosis (p<0.0001)." (PMID 21249220, 2011). "Anthropometrical evaluation and serum C-reactive protein levels in human immunodeficiency virus (HIV)-infected and HIV-uninfected children being treated for tuberculosis on enrolment after 1 month and 4 months of treatment." (PMID 19386087, 2009). "Laboratory investigations, such as ESR and CRP, although suggestive of infective etiology, are not specific to tuberculosis." (PMID 39493199, 2024). "Inflammatory mediators analyzed in combination, including IFN-γ, CRP, and total sialic acid, may be useful in evaluating the systemic inflammatory response in subjects with APTB and TBDM before and after anti-tuberculosis treatment." (PMID 38562330, 2024). "The seven RNA signatures were moderately to highly correlated (Spearman rank coefficients 0·42-0·93) and discriminated tuberculosis culture positivity with similar AUROCs (0·73-0·80), but none statistically better than CRP (AUROC 0·78, 95% CI 0·72-0·83)." (PMID 38583459, 2024). "We performed a systematic search using terms for “C-reactive protein” and “tuberculosis” in OVID Medline on 1st April 2021 with no language or date restrictions." (PMID 36375640, 2023). "Out of 73 participants without tuberculosis, the CRP value was high (≥8.25) for 22 (30.14%) participants and low (<8.24) for 51 (69.86%) participants." (PMID 35806852, 2022). "We analyzed the correlations between TB Ag-Nil and WBC, ESR, CRP and disease duration in a sample of 51 tuberculosis patients and 72 non-tuberculosis patients, respectively, by Spearman’s rho test." (PMID 36204647, 2022).
tuberculosis (continued). "The low specificities of W4SS and CRP concentration are likely to be due to the high prevalences of other opportunistic diseases in patients without tuberculosis in this patient population." (PMID 35338834, 2022). "Therefore, the initial biological workup is classically characterized by: CRP, calcium, antinuclear antibody, antineutrophil cytoplasmic antibody, HIV, and syphilis serologies, as well as screening for tuberculosis." (PMID 36388212, 2022). "The expression of CRP was significantly increased in patients with advanced tuberculosis, but it lacked value in the diagnosis of early tuberculosis." (PMID 35633888, 2022). "Laboratory test: Blood Regular Test: White Blood Cells WBC:9.98*109/L, Erythrocyte Sedimentation Rate (ESR): 15 mm/h, C-reactive protein (CRP): (−), Procalcitonin(−), T-SPOT(−), Anti-tuberculosis antibody (−),Tuberculin purified protein derivative (TPPD): (−), Chest X-ray(−)." (PMID 34980042, 2022). "C-reactive protein reduces the need for further rapid diagnostic tests without compromising sensitivity and has been included in the updated WHO tuberculosis screening guidelines." (PMID 34800394, 2022). "Compared with W4SS, C-reactive protein reduces the need for further rapid diagnostic tests without compromising sensitivity, and it has been included in the updated WHO tuberculosis screening guidelines." (PMID 34800394, 2022). "Out of the 73 participants without tuberculosis, the CRP value was positive for 17 (23.29%) of them and negative for 56 (76.71%)." (PMID 35806852, 2022). "Furthermore, markers elevated in Stage 1, such as CRP and CXCL10/IP-10, have been found to have high sensitivity and moderate specificity to triage patients with symptoms suggestive of active tuberculosis." (PMID 33724185, 2021). "Thus, it confirms that inflammatory reactions are common in tuberculosis patients and that ESR and CRP can be used as indirect indicators of postoperative prognosis." (PMID 34926681, 2021). "Symptoms of tuberculosis such as fever and night sweats are typically not obvious, and the ESR and CRP are often infected by many factors, which restrict the observation of tuberculosis control truly and intuitively." (PMID 33570256, 2021). "We examined the systemic levels of APPs (alpha-2-macroglobulin [⍺-2MG], serum amyloid A [SAA], C-reactive protein [CRP] and haptoglobin [Hp]) in TBL, PTB, latent tuberculosis (LTB) and healthy controls (HC) at baseline and in TBL after the completion of anti-tuberculosis treatment (ATT)." (PMID 32470023, 2020). "Even though inflammatory biomarkers, such as CRP, were not elevated, we should consider the possibility of not only spinal metastases but also tuberculosis when planning surgery involving osteolytic vertebrae." (PMID 32908752, 2020). "Procalcitonin and CRP had ROC AUCs of around 0.7 for discriminating PJP from CAP and tuberculosis in pairwise comparisons, indicating moderate discrimination, but both biomarkers performed less well in discriminating CAP from tuberculosis." (PMID 30107791, 2018). "In addition, C-reactive protein (CRP) is an indicator of disease activity and is often increased in active tuberculosis inflammatory conditions." (PMID 29843631, 2018). "The clinical efficacy was evaluated according to erythrocyte sedimentation rate (ESR), c-reactive protein (CRP), visual analogue scale (VAS), Cobb angle correction, neurological functional recovery, and interbody fusion with bone graft and tuberculosis outcome." (PMID 30345298, 2018). "Median age, body mass index, C-reactive protein, serum amyloid A and were all significantly lower in tuberculosis than in non-tuberculosis patients in univariate analysis after adjustment for multiple testing using the Bonferroni-Holm procedure." (PMID 23185397, 2012). "CRP is a non-specific acute phase reactant and a marker of macrophage activation in active tuberculosis that is increased at diagnosis in proportion to the extent of disease and decreases during and after treatment." (PMID 22238625, 2012).
tuberculosis (continued). "The two CRP assays used showed similar performance characteristics in subgroup analyses of the confirmed tuberculosis group vs. those without confirmed tuberculosis." (PMID 21249220, 2011). "Prescription of an antibiotic before enrolment did not significantly alter the median CRP quotient in subgroup analysis of participants with confirmed, possible and without tuberculosis (p≥0.57, data not shown)." (PMID 21249220, 2011). "Performance of CRP as a screening test: Confirmed tuberculosis vs. those with no tuberculosis (n = 250)." (PMID 21249220, 2011). "Performance of CRP as a screening test: Confirmed tuberculosis vs. those with possible tuberculosis or without tuberculosis (n = 364)." (PMID 21249220, 2011). "C-reactive protein (CRP) is a non-specific inflammatory protein that is usually elevated in patients with tuberculosis, but its role in the diagnosis of tuberculosis is uncertain." (PMID 21249220, 2011). "We evaluated serum CRP in sputum smear-negative tuberculosis suspects in the Umgungundlovu District, KwaZulu-Natal, South Africa." (PMID 21249220, 2011). "Performance of CRP as a screening test: Combined group of confirmed or possible tuberculosis vs. those with no tuberculosis (n = 364)." (PMID 21249220, 2011). "In addition, the range of CRP was wide within several patient groups, including some EBV, tuberculosis and neuroborreliosis patients presenting with a CRP of < 2 mg/l or 2 mg/l and thus giving no obvious indication of on-going infection." (PMID 20626864, 2010). "CRP – C-reactive protein; LDH – lactate dehydrogenase; WBC – white blood cell count; TB – tuberculosis." (PMID 40585722, 2025). "Additionally, screening for other co-infections, such as tuberculosis or bacterial infections which increase CRP level, was not done among the participants." (PMID 38725704, 2024). "Although CRP values have been found to be elevated in HIV-positive individuals both before and after the initiation of ART without underlying tuberculosis, studies have shown that the CRP value is usually <3 mg/dL, irrespective of their immune status (i.e., CD4 count and viral load)." (PMID 35806852, 2022). "Although elevations in CRP (≥10 mg/L) are not specific for active tuberculosis, two studies that evaluated CRP as a screening test among PLHIV initiating antiretroviral therapy (ART) found that CRP has a two- to six-fold higher specificity (58% and 81%) than symptom-based tuberculosis screening." (PMID 35806852, 2022). "His C-reactive protein (CRP), procalcitonin (PCT), erythrocyte sedimentation rate (ESR), and serum ferritin (SF) levels were strikingly high, but evaluations for infectious (such as tuberculosis) or rheumatic conditions (such as giant cell arteritis) were unrevealing." (PMID 35547205, 2022). "Whereas systemic elevation of IL-6 is required for the induction of CRP in hepatocytes, LRG induction is mediated by multiple inflammatory cytokines and is observed not only in the liver but also in the inflamed tissues such as tuberculosis lesions of the lung." (PMID 32099022, 2020). "Hepcidin concentrations were highly correlated with CRP concentrations among hospitalized patients (rho = 0.630; P < .001), ambulatory patients with tuberculosis (rho = 0.621; P < .001), and ambulatory patients without tuberculosis (rho = 0.315; P = .016)." (PMID 26136467, 2016). "The 19 participants with confirmed tuberculosis that was not diagnosed during the initial clinical evaluation had a median CRP quotient of 7.0 (IQR 2.4–16.2) compared to the median CRP quotient of 15.9 (IQR 9.4–24.5) in the 116 participants diagnosed with a focal process (p = 0.0003)." (PMID 21249220, 2011). "In high HIV prevalence settings a normal CRP could be a useful test in combination with clinical evaluation to rule out tuberculosis in ambulatory patients." (PMID 21249220, 2011).